LIFR-AS1 (LIFR antisense RNA 1)
Gene: Long non-coding RNA gene on chromosome 5 (38,556,762 to 38,671,216, forward strand). Ensembl gene ENSG00000244968.
Diseases named in the same sentence as LIFR-AS1 in open-access papers:
LIFR-AS1 is named in the same sentence as 1 disease in open-access papers, as found by Europe PMC text mining. Sharing a sentence is not in itself a finding about the gene and the disease. The quoted sentences say what the papers report.
tumor (1 paper, 2021). "Leukemia inhibitory factor receptor antisense RNA 1 (LIFR-AS1) is a novel tumor-related lncRNA and has been reported as a tumor suppressor in breast cancer." (PMID 33794884, 2021).